KCTD18 (potassium channel tetramerization domain containing 18)
Synonyms: FLJ31322; 6530404F10Rik; FLJ37818
Tractability: PROTAC: ubiquitination databases record sites on it; its protein half-life has been measured.
Gene: Protein-coding gene on chromosome 2 (200,488,956 to 200,519,784, reverse strand). Ensembl gene ENSG00000155729.
Subcellular location (Human Protein Atlas): Mitochondria
Gene Ontology:
Molecular function: identical protein binding
Biological process: protein homooligomerization
Genetic constraint (gnomAD): Loss-of-function variants: 15 observed, 18.19 expected, observed/expected ratio (o/e) 0.82, 90% interval 0.55 to 1.27. The upper end of that interval is the gene's LOEUF score, 1.27, which puts it in group 5 of 6, group 1 being the genes least tolerant of losing a copy. Missense variants: 377 observed, 433.91 expected, observed/expected ratio (o/e) 0.87, 90% interval 0.8 to 0.95. Synonymous variants: 138 observed, 168.66 expected, observed/expected ratio (o/e) 0.82, 90% interval 0.71 to 0.94.
Homologues: Orthologues: chimpanzee KCTD18 (99% identical), macaque KCTD18 (96% identical), rat Kctd18 (81% identical), mouse Kctd18 (80% identical), rabbit KCTD18 (78% identical), dog KCTD18 (74% identical), Drosophila melanogaster twz (12% identical), Caenorhabditis elegans F32B4.5 (9% identical). Paralogues in human: KCTD8 (19% identical), KCTD12 (17% identical), KCTD16 (17% identical), KCTD19 (14% identical), KCTD21 (14% identical), KCTD6 (13% identical), KCNRG (12% identical), KCTD1 (12% identical), KCTD11 (12% identical), KCTD15 (12% identical), KCTD14 (12% identical), KCTD7 (11% identical), and 1 more.
Diseases named in the same sentence as KCTD18 in open-access papers:
KCTD18 is named in the same sentence as 4 diseases in open-access papers, as found by Europe PMC text mining. Sharing a sentence is not in itself a finding about the gene and the disease. The quoted sentences say what the papers report.
restless legs syndrome (1 paper, 2021). A condition that occurs while resting or lying in bed; it is characterized by an irresistible urgency to move the legs to obtain relief from a strange and uncomfortable sensation in the legs. "Finally, KCTD18 has been only potentially associated to Restless Legs Syndrome and no information are available that link KCTD18 to tumor development." (PMID 34001146, 2021).
infection (1 paper, 2025). The state of being infected such as from the introduction of a foreign agent such as serum, vaccine, antigenic substance or organism. "Additionally, genes such as DOCK2, ARHGAP24, and KCTD18 regulate cytoskeletal reorganization and cell migration, ensuring that immune cells effectively reach infection or inflammation sites." (PMID 40098976, 2025).
KCTD18 also shares sentences with these, for which no sentence is quoted: glaucoma (1 paper); tumor (1).